KDM1A (lysine demethylase 1A)
Diseases named in the same sentence as KDM1A in open-access papers (continued):
Sharing a sentence is not in itself a finding about the gene and the disease.
tumor (continued). "We found that xenograft tumors derived from PC9 cells that stably expressed KDM1A shRNA exhibited significantly slower growth rates and smaller tumor sizes, on average, compared to cells expressing the control shRNA." (PMID 27058897, 2016). "In the current study, we demonstrate that KDM1A promotes tumor metastasis both in vitro and in vivo, and its higher expression is significantly correlated with poor prognosis in NSCLC patients." (PMID 27058897, 2016). "Here we demonstrate that KDM1A advances tumor metastasis by epigenetically silencing the TIMP3 transcription, which in turn stimulates MMP2 expression and JNK phosphorylation." (PMID 27058897, 2016). "Here we demonstrate in several tumor cell lines an interaction between KDM1A and both DNMT1 and DNMT3B." (PMID 27449289, 2016). "We found that KDM1A was not only up-regulated in tumors compared to non-tumor controls but also significantly up-regulated in all stages of NSCLC, from stage 1 (T1) to stage 4 (T4)." (PMID 27058897, 2016). "To further investigate the effect of KDM1A knockdown on tumor metastasis in vivo, we established two models using nude mice." (PMID 27058897, 2016). "We and others previously reported that overexpression of KDM1A in several tumor entities correlates strongly with tumor aggressiveness, adverse outcome, and cellular dedifferentiation." (PMID 24252778, 2013). "Because KDM1A is elevated in various tumor types, it is considered an important tumor oncogene." (PMID 40600050, 2025). "A recent study demonstrated that KDM1A promoted tumor progression in CRC through multiple mechanisms, including maintenance of tumor stem cell properties, promotion of cell proliferation and migration, inhibition of apoptosis, and involvement in DNA damage response." (PMID 40699666, 2025). "The knockdown of CoREST2 in an in situ xenograft mouse model resulted in reduced primary tumor growth and lung metastasis, suggesting that disruption of the interaction between KDM1A, CoREST2, and STAT3 serves as a therapeutic strategy to target neuroendocrine differentiation." (PMID 40699666, 2025). "Inhibiting KDM1A’s expression has been reported as a feasible tumor treatment strategy." (PMID 38581529, 2024). "Inhibiting the expression of KDM1A has been reported as a feasible tumor treatment strategy." (PMID 38581529, 2024). "NCL-1 also appears to influence the tumor microenvironment by either destroying and/or preventing vascularization, implying that KDM1A might be regulating tumor angiogenesis and/or vascularization." (PMID 39458030, 2024). "KDM1A inhibition shifted the aggressive tumor cell phenotypes towards less aggressive phenotypes." (PMID 39458030, 2024). "We used the Cox proportional hazards regression method to investigate the effect of covariates such as age, sex, tumor stage, and KDM1A expression on PFS and OS; we obtained a hazard ratio (HR) and 95% confidence interval (CI) for each covariate (univariable and multivariable)." (PMID 37385999, 2023). "Also, evidence reported the critical role of KDM1A in preserving tumor SCs compartment and, consequently, promoting tumor development." (PMID 37385999, 2023). "Finally, our data also revealed that tumours expressing high BAZ2A levels also express high levels of KDM1A and TOP2A, suggesting common regulatory pathways." (PMID 37184661, 2023). "Also, KDM1A silencing resulted in up-regulation of miR-506-3p, previously reported to play a tumor-suppressive role in CRC." (PMID 37385999, 2023). "KDM1A inhibition has also been reported to suppress PC tumor growth in male mice." (PMID 35078526, 2022). "Furthermore, KDM1A, the first identified demethylase, also termed LSD1 or KIAA0601, can regulate the initiation of tumours." (PMID 35814454, 2022). "Besides that BCL2, FKBP8, and KDM1A were increased in tumor compared with normal tissues, we also observed significant correlation between KDM1A and BCL2 protein level." (PMID 35970393, 2022).
tumor (continued). "Given that the circRNA of KDM1A was also overexpressed in tumor tissues, this gene might be a potential focus for future study." (PMID 34857007, 2021). "KDM1A also demethylates Ago2 at the K726me1 site to regulate the tumor T cell response." (PMID 34307695, 2021). "Mechanistically, miR-329-3p inhibits tumor cellular immunosuppression and reinforces the response of tumor cells to T cell-induced cytotoxic effect by targeting KDM1A mRNA and downregulating its expression, which contributed to MEF2D demethylation and activation of PD-L1 expression." (PMID 34307695, 2021). "Interestingly, pharmacological inhibition of LSD1 (lysine-specific histone demethylase 1, also known as KDM1A) suppressed tumor growth in a chemoresistant PDX model, and it coincided with activation of the NOTCH-REST axis and downregulation of ASCL1110." (PMID 31827074, 2019). "However, DNA methylation at cg11637544 in the first exon of KDM2A and at cg26662347 in the 200-kb TSS region of KDM1A elevates corresponding expression in tumor tissues." (PMID 29619118, 2018). "Furthermore, KDM1A inhibition reduces tumor growth, while its overexpression can contribute to human carcinogenesis." (PMID 27449289, 2016). "In this study we show that the microRNA hsa-miR-137 (miR137) tumor suppressor regulates expression of an extended network of transcriptional coregulators including KDM1A/LSD1/AOF1, KDM2A/JHDM1A/FBXL11, KDM4A/JMJD2A, KDM5B JARID1B/PLU1, KDM7A/JHDM1D/PHF8, MED1/TRAP220/DRIP205 and NCoA2/SRC2/TIF2." (PMID 26461474, 2015). "Furthermore, the tumor-promoting effects of KDM1A were also attenuated by HNF4A-liver-TE deletion." (PMID 38965210, 2024). "Importantly, 74% of these BAZ2A-TAM-dependent genes were significantly down-regulated by comparing BAZ2Ahigh/KDM1Ahigh tumours (i.e., 39 PCas that scored as the top 25% with the highest BAZ2A and KDM1A expressions, respectively) compared with BAZ2Alow/KDM1Alow tumours (41 PCas)." (PMID 37184661, 2023). "We suggested that KDM1A could become a new prognostic biomarker for antitumor immunotherapy, and the combination of KDM1A inhibitors and immunotherapy could exert a potent efficacy of tumor suppression." (PMID 34925656, 2021). "To investigate whether we could further enhance FAS levels on the tumor cells, we combined the KDM1A inhibitor treatment with low-dose irradiation (2 Gy), but the combination therapy did not induce higher FAS expression levels than KDM1A inhibitor treatment alone." (PMID 34771652, 2021). "Therefore, our analysis suggests that high KDM1A and low TIMP3 expressions may promote tumor metastasis, which is associated with poor NSCLC prognosis." (PMID 27058897, 2016). "KDM1A also demethylates H3K4me1/2 at the promoter of GADD45B, suppressing its apoptotic function and enhancing tumor survival." (PMID 40057667, 2025). "Pioneering research has shown that lysine‐specific demethylase 1 (LSD1, also known as KDM1A) suppressed endogenous double‐stranded RNA (dsRNA) and interferon (IFN) responses in tumour cells." (PMID 40356247, 2025). "KDM1A demethylates H3K4 at the promoters of Prickle1 and APC, silencing these tumor-suppressor genes and driving the β-catenin pathway, which promotes stemness and chemoresistance." (PMID 40057667, 2025). "For example, the inhibition of KDM1A was observed to prevent pioneer factor FOXA1 from binding chromatin, thereby decreasing AR activity and suppressing tumor growth." (PMID 38254784, 2024). "Previously, it was reported that patients with high tumor expression levels of EZH-2, EHMT2/G9a, KDM3A, KDM4B, and LSD1/KDM1A had significantly worse prognoses." (PMID 38785960, 2024).
tumor (continued). "Deep mutational interaction perturbation scanning of NF2 with conformation-dependent interaction partners KDM1A, EMILIN, and PIK3R3 revealed two regions critical for NF2 tumor suppressor function." (PMID 37280085, 2023). "This is result is also consistent with the fact that about 50% of BAZ2Ahigh/KDM1Ahigh and BAZ2Ahigh/TOP2Ahigh corresponds to tumours with high TOP2A and KDM1A expression levels, respectively (Q1)." (PMID 37184661, 2023). "The results showed that KDM1A exhibited a high level of expression in LIHC tissues, compared with that in NATs, and its expression increased along with the stages of tumor progression." (PMID 37250145, 2023). "The lncRNA MAGI2-AS3 interacts with KDM1A and promotes histone demethylation of histone H3 lysine 4 (H3K4me2) in the RACGAP1 promoter region, and silencing RACGAP1 inhibits tumor growth in vivo." (PMID 35205612, 2022). "Similar changes in TME are also observed in tumor tissues treated with other agents, such as inhibitors of KMT6A (EZH2), KDM1A (LSD1), PRMT5, and BET proteins." (PMID 35935878, 2022). "Another example showed KDM1A can demethylate K185 of transcription factor E2F1 which has an important role in regulating the cell cycle and tumor suppressor genes in lung cancer cells." (PMID 34220955, 2021). "In support of KMT2D’s role as a tumor suppressor in cSCC, inhibition of the histone demethylase enzyme that opposes KMT2D’s function, LSD1 (KDM1A), has been shown to both promote epidermal differentiation and suppress cSCC in 3D human cSCC organoids." (PMID 34298617, 2021). "KDM1A can apparently inhibit the expression of TIMP1 by demethylating H3K4ME2 in the TIMP1 promoter region, activating MMP9, which is responsible for tumor migration and PTC invasion through this pathway." (PMID 34055497, 2021). "Treatment with vorinostat (HDAC inhibitor) and tranylcypromine (histone lysine demethylase KDM1A inhibitor) decreased GBM stem cell proliferation and led to significant tumor regression in mouse models." (PMID 34198989, 2021). "Our findings show that epigenetic reprograming by an epigenetic modification, KDM1A, plays an important role in mediating recruitment of CD8 + T cells to the tumor site." (PMID 33799951, 2021). "KDM1A (LSD1) is important for epithelial-to-mesenchymal transition (EMT) and promotes the progression of tumor." (PMID 31766427, 2019). "Moreover, Tumor, Normal, and Metastasis (TNM) plot analysis from TCGA showed that the expression of KDM1A network genes, including STAT3 and CTLA4, was higher in HNSCC clinical tumors than in normal human tissues." (PMID 40246812, 2025). "Therefore, if KDM1A exerts a suppressive effect on NF-κB proinflammatory signaling in ESCC, it is reasonable to think that it will block STING mediated anti-tumor immunity from the TME." (PMID 39638799, 2024). "Furthermore, to assess the protein expression levels of KDM1A, KDM5A, and KDM5B in human tumor tissue, we conducted IHC on a tumor tissue microarray." (PMID 39239542, 2024). "In contrast, the expression of KDM1A between metastatic PCa relative to localized tumour and normal tissue was less consistent between the two different datasets." (PMID 37184661, 2023). "KDM1A-inhibited but not untreated tumor cells were selectively killed by activated T cells, resulting in a ratio shift towards the untreated tumor cells in the resulting population." (PMID 34771652, 2021). "KDM1A inhibitor doses as low as 0.5 μM could induce FAS expression on tumor cells, and FAS upregulation by the KDM1A inhibitor remained stable for up to 48 h after inhibitor removal, allowing subsequent T cell treatment to test combination therapy." (PMID 34771652, 2021).
tumor (continued). "Considering the many similarities in cellular processes such as proliferation, migration and invasion between tumor progression and placental development, it is not surprising KDM1A also is present in placenta." (PMID 33029224, 2020). "However, in the first set of results, HDM genes (KDM1A, KDM5B, KDM6A and KDM7C) were mostly overexpressed in tumour tissue comparatively to normal oesophageal epithelium." (PMID 32429269, 2020). "The TF–target gene network analysis uncovered an unexpected scenario where both correlation-enhancing genes (with higher correlation in the tumor) and -repressing genes (with lower correlation in the tumor) were targeted by STAT1 (6A), STAT3 (6B), KDM1A (6C), PML and RELA." (PMID 33384992, 2020). "This noncoding RNA interacts with the KDM1A/CoREST complex, mediates its interaction with the polycomb repressive complex 2 (PRC2), and assists in its recruitment to the HOXD locus to downregulate the expression of tumor-suppressor genes." (PMID 29921310, 2018). "KDM1A was not expressed in the normal cerebellar tissue or in nonmalignant cells in the tumor samples, such as stromal tissue." (PMID 24252778, 2013). "Differential expression analysis revealed that STING, which plays a pivotal role in mediating NF-κB signaling-dependent anti-tumor immune responses, was negatively related to KDM1A in sTILs (p = 0.0261), rather than in ESCC, which was further supported by immunostaining data (p = 0.0359)." (PMID 39638799, 2024). "Therefore, we were interested in investigating whether KDM1A, KDM5A, and KDM5B expression was correlated with the enrichment of tumor-infiltrating lymphocytes in PC." (PMID 39239542, 2024). "Our analysis of tumor RNA-seq data from the mouse AST model (KrasG12D/+; Lkb1fl/fl, KL) showed that multiple epigenetic regulators including LSD1 (lysine-specific histone demethylase 1, also known as KDM1A) were up-regulated in squamous lesions compared to adenomatous lesions." (PMID 37051524, 2023). "However, the analysis of a large cohort of primary PCa and metastatic castration resistant PCa (CRPC) (333 and 118 tumours, respectively) revealed a significant positive correlation of both TOP2A and KDM1A levels with BAZ2A expression in both metastatic and primary tumors." (PMID 37184661, 2023). "Importantly, KDM1A exerts these effects by epigenetically silencing TIMP3 transcription, which in turn increases MMP2 expression in the extracellular matrix (ECM) and JNK phosphorylation in the cytoplasm of tumor cells, thus contributing to cell invasion and migration in NSCLC." (PMID 27058897, 2016). "Overall, our results indicate that KDM1A impacts CRC progression in several non-overlapping ways, and therefore it represents a promising epigenetic target to prevent tumor relapse." (PMID 37385999, 2023). "Interestingly, there was no significant changes between tumor and normal tissue in enzymes writing or erasing H3K4 marks including Kmt2a, Ash1l, Cxxc1, Kdm1a and Ezh2." (PMID 25823816, 2015). "Results showed that KDM1A expression implies a poorer prognosis on PFS (HR: 3.47, 95% CI: 1.14–10.57, p = 0.0289) and a worse OS (HR: 7.67, 95% CI: 1.95–1.03, p = 0.0036), while the remaining covariates (age, sex, tumor stage) showed no statistical significance on PFS and OS (all p > 0.05)." (PMID 37385999, 2023). "The previously identified TFs—STAT1, STAT3, KDM1A, PML RELA, and TBL1XR1—did not exhibit a deviating correlation between the early and late tumor stages, indicating that their correlation remains constant throughout the different stages of the tumor compared to non-tumor tissues." (PMID 33384992, 2020).
infection (26 papers, 2013 to 2025). The state of being infected such as from the introduction of a foreign agent such as serum, vaccine, antigenic substance or organism. "Finally, and in view of recent report pinpointing at the infection with Epstein Barr virus as one of the leading potential causes for MS, it is worth mentioning that inhibitors of KDM1A have been shown to be active against other members of the family of Herpesviridae." (PMID 35890315, 2022).
hematologic malignancies (17 papers, 2013 to 2025). "For instance, the effect of a LSD1/KDM1A selective inhibitor (ORY-1001) was evaluated in patients with blood disorders." (PMID 38225241, 2024). "Secondly, in terms of clinical applications, LSD1/KDM1A is aberrantly overexpressed in several cancer types, with different LSD1 inhibitors currently developed to treat solid tumors and hematological malignancies." (PMID 36840175, 2023). "The histone demethylase KDM1A (LSD1), a component of the CoREST corepressor complex, is highly expressed in hematologic malignancies and regulates hematopoietic differentiation." (PMID 41279630, 2025). "Outside the 2OGDD family, another histone demethylase with relevance to hematologic malignancies, KDM1A (LSD1), uses FAD as a cofactor." (PMID 34204821, 2021).
adenocarcinoma (9 papers, 2017 to 2025). A common cancer characterized by the presence of malignant glandular cells. "Supporting our observations, CTBP monomers have been reported to lose the interaction with KDM1A in a mechanistic study in the human adenocarcinoma cell line HuTu80." (PMID 40490364, 2025).
neurodegenerative disease (9 papers, 2013 to 2025). A disorder of the central nervous system characterized by gradual and progressive loss of neural tissue and neurologic function. "Pathways related to epigenetic signaling, and synapse maturation, such as HDAC and KDM1A were upregulated in FRDA; inhibitors of these genes have been explored for neurodegenerative diseases, including FRDA." (PMID 38420191, 2024). "Some scholars reported that the depletion of KDM1A increased the expression level of sestrin-2 (SESN2) and then resulted in the inhibition of mTOR complex 1 (mTORC1), which was good for sustainability of cellular homeostasis and was a protective mechanism against neurodegenerative diseases." (PMID 33987474, 2020).
psychiatric disorder (4 papers, 2022 to 2025). A disorder characterized by behavioral and/or psychological abnormalities, often accompanied by physical symptoms. "Vafidemstat is a clinical stage inhibitor of KDM1A in development for the treatment of neurodegenerative and psychiatric diseases." (PMID 35890315, 2022).
vascular disorder (2 papers, 2020 to 2023). A general term used to describe any disease affecting blood vessels]. "We speculate that an in‐depth understanding of the functions and implications of KDM1A will offer insights into the development of innovative strategies for the treatment of vascular disorders." (PMID 31737960, 2020). "A thorough understanding of the precise relationship between KDM1A and BMP‐2 will allow us to develop effective strategies for targeted local delivery of KDM1A‐based agents with therapeutic potential against neointimal hyperplasia and other vascular disorders." (PMID 31737960, 2020).
KDM1A also shares sentences with these, for which no sentence is quoted: pancreatic cancer (18 papers); osteosarcoma (13); acute promyelocytic leukemia (8); diabetic retinopathy (8); Anxiety (7); embryonic carcinoma (7); esophageal squamous cell carcinoma (7); neurological disorders (7); acute lymphoblastic leukemia (6); anemia (6); autism (6); myelodysplastic syndrome (6); oral squamous cell carcinoma (6); osteoporosis (6); teratocarcinoma (6); chondrosarcoma (5); essential thrombocythemia (5); hematological cancers (5); Hyperglycemia (5); Merkel cell carcinoma (5); Pancytopenia (5); retinoblastoma (5); rhabdomyosarcoma (5); blood cancers (4); endometriosis (4); Hypertension (4); multiple sclerosis (4); myeloid malignancies (4); renal cell carcinoma (4); rheumatoid arthritis (4).
A further 182 diseases each share a sentence with KDM1A in 4 papers or fewer.